INMT (indolethylamine N-methyltransferase)
Description:
Functions as a thioether S-methyltransferase and is active with a variety of thioethers and the corresponding selenium and tellurium compounds, including 3-methylthiopropionaldehyde, dimethyl selenide, dimethyl telluride, 2-methylthioethylamine, 2-methylthioethanol, methyl-n-propyl sulfide and diethyl sulfide. Plays an important role in the detoxification of selenium compounds (By similarity). Catalyzes the N-methylation of tryptamine and structurally related compounds.
Synonyms: TEMT
Tractability: Small molecule: a structure with a bound ligand is known; a high-quality ligand is known; it has a binding pocket of medium quality. PROTAC: a small molecule that binds it is known.
Target class: Enzyme; Transferase
Gene: Protein-coding gene on chromosome 7 (30,697,985 to 30,757,602, forward strand). Ensembl gene ENSG00000241644.
Subcellular location: Cytoplasm
Subcellular location (Human Protein Atlas): Golgi apparatus; Vesicles
Pathways (Reactome):
Metabolism: Methylation of MeSeH for excretion
Gene Ontology:
Molecular function: amine N-methyltransferase activity; protein binding; N-methyltransferase activity; dimethyl selenide methyltransferase activity; methyltransferase activity; S-adenosylmethionine-dependent methyltransferase activity; thioether S-methyltransferase activity
Biological process: amine metabolic process; methylation; selenium compound metabolic process
Cellular component: cytosol; cytoplasm
Genetic constraint (gnomAD): Loss-of-function variants: 11 observed, 12.37 expected, observed/expected ratio (o/e) 0.89, 90% interval 0.56 to 1.47. The upper end of that interval is the gene's LOEUF score, 1.47, which puts it in group 6 of 6, group 1 being the genes least tolerant of losing a copy. Missense variants: 316 observed, 348.04 expected, observed/expected ratio (o/e) 0.91, 90% interval 0.83 to 1. Synonymous variants: 155 observed, 148.33 expected, observed/expected ratio (o/e) 1.04, 90% interval 0.92 to 1.19.
Homologues: Orthologues: chimpanzee INMT (99% identical), macaque INMT (94% identical), rabbit INMT (89% identical), mouse Inmt (58% identical), rat Inmt (58% identical), pig INMT (57% identical), zebrafish zgc:64002 (38% identical), Caenorhabditis elegans anmt-2 (29% identical), Caenorhabditis elegans anmt-3 (27% identical), Caenorhabditis elegans anmt-1 (22% identical). Paralogues in human: NNMT (53% identical), PNMT (36% identical).
Diseases named in the same sentence as INMT in open-access papers:
INMT is named in the same sentence as 37 diseases in open-access papers, as found by Europe PMC text mining. Sharing a sentence is not in itself a finding about the gene and the disease. The quoted sentences say what the papers report.
prostate carcinoma (10 papers, 2017 to 2025). A carcinoma that arises from epithelial cells of the prostate gland. "INMT downregulation has been observed in other types of cancer, such as meningioma, prostate cancer, and uterine corpus endometrial carcinoma, and is associated with poor overall survival." (PMID 41008295, 2025). "We performed pathway enrichment analysis on TCGA-PRAD and GSE46602 cohorts and found that INMT was closely associated with prostate cancer progression and was involved in regulating the MAPK, TGFβ, and Wnt signaling cascades." (PMID 35252179, 2022). "In cancer, INMT exhibits dual roles, either promoting drug resistance (as in prostate cancer) or acting as a tumor suppressor (as in hepatocellular carcinoma and NSCLC), suggesting a context-specific effect tied to its methylation capacity." (PMID 41008295, 2025). "The results show that the overexpression of INMT resulted in a poor prognosis for clinical prostate cancer." (PMID 41008295, 2025). "Studies suggested that the expression of INMT is downregulated in lung cancer, meningioma, and prostate cancer." (PMID 35252179, 2022). "We found that INMT negatively regulated the TGFβ signaling pathway and was the most significant in a hormone-resistant prostate cancer cell line (PC-3)." (PMID 35252179, 2022). "After overexpression of INMT in prostate cancer cell lines 22Rv1 and PC-3, we confirmed that INMT inhibited MAPK, TGFβ, and Wnt signaling pathways, inhibited the proliferation of prostate cancer cells, and promoted apoptosis." (PMID 35252179, 2022). "By analyzing the correlation between proliferation and apoptosis genes and proteins and in vitro experiments, we found that the expression of INMT affected the proliferation and apoptosis of prostate cancer cells." (PMID 35252179, 2022). "To verify the biological roles of INMT in prostate cancer, we used real-time cell analysis (RTCA) and the Cell Counting Kit 8 (CCK8) assays to determine the role of INMT in prostate cancer cell proliferation." (PMID 35252179, 2022). "Research has shown that when INMT is overexpressed in prostate cancer cells, INMT inhibits cell proliferation and induces apoptosis by activating MAPK, TGFβ, and Wnt signaling pathways." (PMID 36186458, 2022). "Researchers found that INMT levels were lower in lung, meningioma, and prostate cancers; however, the role of INMT in cancer is unclear." (PMID 36186458, 2022). "It has been reported that the expression of INMT is downregulated in lung cancer, prostate cancer, and meningioma." (PMID 36437916, 2022). "After overexpression of INMT in prostate cancer cell lines 22Rv1 and PC-3, we found an effect of INMT on these tumor signal pathways; overexpression of INMT inhibited the proliferation of prostate cancer cells and promoted apoptosis." (PMID 35252179, 2022). "Reduced expression of INMT has been associated with enhanced non-small cell lung cancer (NSCLC) adenocarcinomas and prostate cancer." (PMID 34069906, 2021). "Other studies revealed the relationship between INMT expression and prostate cancer." (PMID 41008295, 2025). "Interestingly, INMT expression was found to be lower in early-stage prostate cancer but increased in castration-resistant prostate cancer." (PMID 40358182, 2025). "Deregulation of INMT expression in primary lung cancer and prostate cancer has been reported." (PMID 37202783, 2023). "To verify the effect of INMT on these pathways, we transfected hormone-sensitive prostate cancer cells (22Rv1) and hormone-resistant prostate cancer cells (PC-3) with INMT overexpression lentiviral vector or the corresponding negative control lentiviral vector." (PMID 35252179, 2022). "Identification of potential therapeutic agents based on the expression of INMT in prostate cancer." (PMID 35252179, 2022). "In conclusion, INMT is expressed at a low level in prostate cancer and may affect the apoptosis and proliferation of prostate cancer cells through the MAPK, TGFβ, and Wnt signaling pathways." (PMID 35252179, 2022).
prostate carcinoma (continued). "Studies suggested that the expression of INMT is downregulated in lung cancer, meningioma, and prostate cancer; however, its role and mechanism in cancer, especially prostate cancer, remain unclear." (PMID 35252179, 2022). "Kruskal−Wallis test and clinical correlation assessment were carried out on TCGA-PRAD and exhibited that the RNA expression of INMT in prostate cancer with lymph node metastasis was significantly lower than that of patients without lymph node metastasis (p < 0.01)." (PMID 35252179, 2022). "Indolethylamine-N-methyltransferase (INMT) is a methyltransferase downregulated in lung cancer, meningioma, and prostate cancer; however, its role and mechanism in prostate cancer remain unclear." (PMID 35252179, 2022). "INMT was previously identified as predicting disease progression risk in prostate cancer whereas MAT2B has not previously been implicated in prostate cancer risk or etiology." (PMID 28216563, 2017). "Interestingly, it has also been reported that INMT downregulation may contribute to lung and prostate cancer." (PMID 41008295, 2025). "Similarly, prostate cancer patients with elevated INMT levels may exhibit a high drug sensitivity to another 14 compounds." (PMID 35252179, 2022). "To exclude the possibility that the highly increased expression of INMT in CRPC is model-specific, we established another PCa xenograft mouse model, in which an AR-positive and androgen-sensitive human prostate cancer cell line, LNCaP, was employed." (PMID 34587977, 2021). "We found that the expression of INMT was highly increased in CRPC and was correlated with poor prognosis of clinical prostate cancer (PCa)." (PMID 34587977, 2021). "By analyzing TCGA-PRAD, we found that the RNA expression of INMT was remarkably lower in diverse stages of prostate cancer in contrast with the adjacent non-cancerous prostate tissues (p < 0.001)." (PMID 35252179, 2022). "In the present study, we analyzed The Cancer Genome Atlas (TCGA)-PRAD and found that the expression of INMT in prostate cancer was lower than that of adjacent non-cancerous prostate tissues." (PMID 35252179, 2022). "Congruent with TCGA, the content of INMT protein in the prostate cancer tissues was reduced, in contrast with the adjacent non-cancerous prostate tissues (p < 0.01)." (PMID 35252179, 2022). "To confirm the difference in the transcription level of INMT in prostate cancer and adjacent non-cancerous prostate tissues analyzed in TCGA, we used western blotting to assess the levels of INMT protein in 30 pairs of prostate cancer and adjacent non-cancerous prostate tissues." (PMID 35252179, 2022). "By analyzing The Cancer Genome Atlas (TCGA)-PRAD, we found that the expression of INMT in prostate cancer was lower than that of adjacent non-cancerous prostate tissues and was significantly correlated with lymph node metastasis Gleason score, PSA expression, and survival." (PMID 35252179, 2022). "The expression of INMT was significantly negatively correlated with lymph node metastasis, Gleason score, and PSA level, suggesting that INMT may be involved in the biological processes of prostate cancer proliferation, migration, and invasion." (PMID 35252179, 2022).
lung carcinoma (7 papers, 2016 to 2025). "Additionally, INMT is highly expressed in the lung, where its dysregulation has been implicated in certain lung cancers." (PMID 41008295, 2025). "On the other hand, SYNPO2, ADH1B and INMT were found to be repressed in HIV-associated lung cancer." (PMID 30177858, 2018). "At the same time, we also found that 11 of 17 (64.7%) tumors had decreased ADH1B mRNA (20.93-fold) or INMT mRNA (10.22-fold) in HIV lung cancer." (PMID 30177858, 2018). "The results demonstrate that INMT mRNA expression was downregulated in HIV lung cancer patients." (PMID 41008295, 2025). "INMT expression has been reported to be dysregulated in lung cancer, meningioma, and PCa." (PMID 38555451, 2024). "In prostate and lung cancer, INMT expression has been found to be downregulated." (PMID 27096627, 2016). "However, the role of INMT and its molecular mechanism in cancer, especially lung cancer, remain unknown." (PMID 36437916, 2022). "We also found decreased ADH1B, INMT and SYNPO2 mRNA levels in HIV lung cancer." (PMID 30177858, 2018).
meningioma (5 papers, 2016 to 2024). A generally slow growing tumor attached to the dura mater. "INMT had been identified as the top hub gene among 8000 genes which were analyzed by the TCNG database consortium on a set of 85 meningiomas." (PMID 27096627, 2016). "Although RF predicts TIMP3, INMT and SLC16A1 followed by ALPL as the important feature genes in subtype 3, the expressions of these three genes are not consistently lower or higher than all other subtypes of meningioma, which restricts their potent of being biomarkers for meningioma." (PMID 33807688, 2021).
liver cancer (4 papers, 2023 to 2025). An epithelial or non-epithelial malignant neoplasm that arises from the liver. "In our study, we demonstrate that the expression of INMT is lower in liver cancer, which is consistent with the finding of Carlos and his colleagues." (PMID 37202783, 2023). "On the other hand, altered INMT expression might play a role in carcinogenesis; reduced INMT levels have been observed in lung adenocarcinoma, and INMT downregulation has been observed in prostate and liver cancers." (PMID 41008295, 2025). "For instance, INMT is downregulated in malignancies such as lung and liver cancer, where its low expression correlates with poor prognosis and may contribute to tumor proliferation through impaired detoxification of bioactive amines." (PMID 41008295, 2025). "Knockdown of INMT significantly promoted liver cancer cell proliferation and colony formation." (PMID 37202783, 2023). "On the basis of the expression of the newly edited and generated ED_miR-3144(3_A < G) target gene was reduced as liver cancer progressed, five candidates, INMT, GHR, GLYAT, SLC38A4, and HMGCS2, were identified through target prediction and expression pattern analyses." (PMID 36599932, 2023). "Likewise, another study demonstrated that INMT knockdown significantly increased liver cancer cell proliferation and colony establishment, suggesting that INMT might act as a tumor-suppressing agent in hepatocellular carcinoma." (PMID 41008295, 2025). "Notably, INMT, ANO1 and GCNT3 have recently been implicated in other types of cancer, which could potentially impact the outcomes of liver cancer." (PMID 39628446, 2024). "All these results indicate that INMT may function as a tumour suppressor in HCC and that INMT affects liver cancer cell proliferation." (PMID 37202783, 2023).
amyotrophic lateral sclerosis (2 papers, 2021 to 2025). Amyotrophic lateral sclerosis (ALS) is a neurodegenerative disease characterized by progressive muscular paralysis reflecting degeneration of motor neurons in the primary motor cortex, corticospinal tracts, brainstem and spinal cord. "Beyond its neuropsychiatric involvement, INMT has also been associated with neurodegenerative diseases such as Alzheimer’s and amyotrophic lateral sclerosis (ALS)." (PMID 41008295, 2025). "INMT has been suggested as a therapeutic target for the treatment of amyotrophic lateral sclerosis (ALS) and schizophrenia." (PMID 34587977, 2021).
breast carcinoma (2 papers, 2020 to 2021). "In addition, we identified five ceRNA pairs (i.e., CDH5 with FAM212B, CDH5 with GYG2 in Module 45, TRIB1 with IL33, TRIB1 with INMT, and TRIB1 with MMRN1 in Module 110) that can be used as prognostic markers of breast cancer in BRCA-associated modules." (PMID 32256525, 2020).
endometrial cancer (2 papers, 2012 to 2022). Primary or metastatic malignant neoplasm involving the endometrium (mucous membrane that lines the endometrial cavity). "Another study examined the role of PTEN in endometrial cancer and found that deregulation of the INMT gene is linked to the absence of PTEN." (PMID 36186458, 2022).
head and neck squamous cell carcinoma (2 papers, 2022). A squamous cell carcinoma that arises from any of the following anatomic sites: lip and oral cavity, nasal cavity, paranasal sinuses, pharynx, larynx, and salivary glands. "Nevertheless, the expression of INMT and its relationship to methylation and immune infiltrates in head and neck squamous cell carcinoma (HNSC) remains a mystery." (PMID 36186458, 2022).
hepatocellular carcinoma (2 papers, 2023 to 2025). A malignant tumor that arises from hepatocytes. "Transcriptome analysis of hepatocellular carcinoma rat models revealed reduced expression of the INMT gene and its encoding protein." (PMID 41008295, 2025). "Studies have shown that the expression of INMT is downregulated in hepatocellular carcinoma." (PMID 41008295, 2025). "This study aimed to identify a selenium metabolism regulator-based prognostic signature for hepatocellular carcinoma (HCC) and validate the role of INMT in HCC." (PMID 37202783, 2023).
lung adenocarcinoma (2 papers, 2022 to 2025). A carcinoma that arises from the lung and is characterized by the presence of malignant glandular epithelial cells. "Additionally, Kaplan–Meier survival analysis revealed a correlation between the decline in INMT expression and poor clinical outcomes in lung adenocarcinoma (LUAD) patients." (PMID 41008295, 2025).
psychosis (2 papers, 2012 to 2025). "This pathway is normally associated with brain activity and psychosis but some studies have found a link between INMT expression and cancer." (PMID 22075945, 2012). "Alterations in INMT expression and/or activity have been correlated with neurological conditions and psychotic disorders." (PMID 41008295, 2025). "It is worth mentioning that most of the current literature focuses on INMT inhibition due to its implications in cancer progression and psychosis-related pathways." (PMID 41008295, 2025). "The pharmacological relevance of INMT inhibitors is underscored by their potential role in modulating pathologies where INMT level and/or activity is upregulated, particularly for psychotic disorders, and various malignancies." (PMID 41008295, 2025).
schizophrenia (2 papers, 2021 to 2025). A major psychotic disorder characterized by abnormalities in the perception or expression of reality. "Some of these hypotheses suggest that INMT may play a role in schizophrenia, offering a potential target to overcome its devastating effects." (PMID 41008295, 2025). "Several hypotheses, including but not limited to the transmethylation hypothesis, suggested that INMT is a contributing factor in schizophrenia and stress-related psychoses." (PMID 41008295, 2025). "Due to the influence of DMT on dopamine regulation, targeting INMT may be a promising strategy for modulating dopaminergic activity in schizophrenia." (PMID 41008295, 2025). "INMT activity is increased in schizophrenia and stress-related psychoses in humans." (PMID 34587977, 2021). "In addition to the transmethylation hypothesis, another hypothesis suggesting INMT might be involved in schizophrenia is the dopamine hypothesis." (PMID 41008295, 2025). "Several studies discussed the role of INMT activity and its metabolite DMT in some medical disorders, including schizophrenia and stress-related psychoses." (PMID 41008295, 2025). "Notably, INMT is highly expressed in the adrenal glands, supporting the early hypothesis that a metabolic disorder involving these glands could play a role in the pathophysiology of schizophrenia." (PMID 41008295, 2025). "Dysregulation in the enzymatic activity of INMT results in elevated levels of methylated indole alkylamines, including DMT and its psychoactive analogs, such as 5-hydroxy-DMT (bufotenine) and 5-methoxy-DMT, in individuals with schizophrenia." (PMID 41008295, 2025).
Alzheimer disease (1 paper, 2025). A progressive, neurodegenerative disease characterized by loss of function and death of nerve cells in several areas of the brain leading to loss of cognitive function such as memory and language. "In contrast, conditions such as Alzheimer’s disease and ALS involve INMT’s interaction with sigma-1 receptors and neuroprotective signaling, highlighting its relevance beyond neurotransmitter methylation." (PMID 41008295, 2025).
depression (1 paper, 2022). "Among them, except for PGM1, PMM2, and INMT, the expression of the other 7 proteins were significantly upregulated in susceptible mice, suggesting the potential role of these molecules in the pathogenesis of CSDS-induced depression in mice." (PMID 36291201, 2022).
Hirschsprung disease (1 paper, 2025). Hirschsprung disease (HSCR) is a congenital intestinal motility disorder that is characterized by signs of intestinal obstruction due to the presence of an aganglionic segment of variable extent in the terminal part of the colon. "Meanwhile, genetic polymorphisms in INMT, such as His46Pro, underline the enzyme’s developmental significance, as seen in Hirschsprung’s disease." (PMID 41008295, 2025). "The human INMT gene is located on chromosome 7 and encodes a protein that exhibits variations, such as the substitution of histidine at position 46 with proline (His46Pro), an example of a single-nucleotide polymorphism (SNP), which may lead to Hirschsprung’s disease." (PMID 41008295, 2025).